CCL8 (C-C motif chemokine ligand 8)
Diseases named in the same sentence as CCL8 in open-access papers (continued):
Sharing a sentence is not in itself a finding about the gene and the disease.
tumor (continued). "Collectively, these insights position Mac_Ccl8 as a potential therapeutic target to mitigate the immunosuppressive impact of hypofractionated radiotherapy in tumor microenvironment." (PMID 38528587, 2024). "Next, cell–cell communication network detected 26 signaling pathways between tumor cells and myeloid cells, and that Mac_Ccl8 was the major source communicating each other in macrophage populations." (PMID 38528587, 2024). "Meanwhile, Cxcl10 has inhibitory effect on tumor progression, Cxcl12, Cxcl14, Ppbp, Pf4 and Ccl8 play an important role in promoting tumor progression." (PMID 38622609, 2024). "TAM recruitment is particularly important and CCL7 and CCL8 can also attract tumour-infiltrating lymphocytes." (PMID 39146303, 2024). "In another example, CCL8 produced by TAMs also upregulate tumor cell secretion of colony stimulating factor 1 (CSF-1) which is crucial to macrophage and DC survival and differentiation through signaling via CSF-1R." (PMID 37114134, 2023). "Further, neutralizing antibodies targeting CCL8 inhibited the pro-tumor migratory effect of hypoxic TAMs." (PMID 37884960, 2023). "CA12 inhibitor dwindles TAMs infiltration and CCL8 production, attenuating tumor growth and metastasis with growing proportion of CD8+T cells, thus showing more notable efficacy in combination with anti‐PD‐1 therapy than monotherapy." (PMID 38098217, 2023). "The GLUT3‐dependent glycolysis metabolism of TAMs has been reported to confer resistance to 5‐FU by increasing the secretion of CCL8 in tumour cells." (PMID 37608500, 2023). "The mRNA level of CCL8 in tumor-infiltrating monocytes was also found to be positively correlated with VIM, negatively with cadherin 1 (CDH1), and positively with the metastatic potential of HCC." (PMID 37006233, 2023). "For example, TAGLN2, CCND2, and CCL8 were identified in the study and were previously well-established as tumor suppressor genes." (PMID 38234400, 2023). "In this study, we demonstrated that APN KO BMSCs highly migrated into the EL-4 tumor mass and secreted CCL8, resulting in the recruitment of CD8+ T cells." (PMID 37370133, 2023). "We found freshly sorted PDGFB tumor cells expressed higher levels of Ccl2, Ccl7, Ccl8, and Ccl12 relative to the same cells maintained in vitro (up to 6 passages) under both GSC and FBS conditions (P < 0.05)." (PMID 37733448, 2023). "CCR1, CCR2B, CCR3, and CCR5 are receptors for CCL8 that are expressed in both immune and tumor cells and play pro-cancer and anti-cancer roles." (PMID 38136340, 2023). "Collectively, these results suggest that FMD inhibits the secretion of pro-tumor cell migration cytokine CCL8 by TAMs induced by hypoxia via mTOR-HIF-1α-glycolysis pathway." (PMID 37884960, 2023). "After polarization, M2 macrophages secreted abundant CCL8 and accelerated tumor progression and metastasis through the CCR5/mTOR pathway." (PMID 38136340, 2023). "After polarization, M2 macrophages secreted abundant CCL8 and accelerated tumor progression and metastasis through the CCR5/mTORC1 pathway." (PMID 38136340, 2023). "Combining the results of previous studies, it is likely that in DLBCL, CCL8 is able to recruit M2 macrophages to promote tumor metastasis." (PMID 36072582, 2022). "Four hub mRNAs in this network, including CXCL10, CXCL11, CCL7, and CCL8, were identified which have also been demonstrated to influence the tumor microenvironment and infection status." (PMID 36544484, 2022). "A high ratio of CD8+ T cells within the tumor areas in relation to the total T cells in the stroma was correlated with CCL8 secretion." (PMID 35954489, 2022). "As the function of TAMs on tumor metastasis is largely dependent on cytokines released, we next showed that CCL8 is responsible for the movement of cell clusters induced by TAMs in luminal-like BrCas." (PMID 35680853, 2022).
tumor (continued). "Further investigations should be conducted to clarify the relationship between tumor-infiltrating macrophages and CCL8 expression, especially in tumor metastasis-related pathways and TAM-dependent angiogenesis." (PMID 36072582, 2022). "The upregulation of CCL8 in tumor-derived monocytes was further confirmed through ELISA and immunofluorescence analysis." (PMID 35362480, 2022). "Accordingly, the levels of CCL8 expression were found to be positively correlated with those of CA12 in tumor-derived monocytes and macrophages and with the metastatic potential of HCC cells." (PMID 35362480, 2022). "Compared with adjacent tissues, the expression level of CCL8 was significantly upregulated in HCC tumor tissues based on the TCGA LIHC dataset." (PMID 35281057, 2022). "CCL8 and Leptin were specifically secreted in the juxta-tumor supernatants at heterogeneous concentrations." (PMID 36539890, 2022). "Several studies have shown that CCL5 and CCL8 promote cancer cell proliferation and migration as well as the recruitment of T regulatory cells, which leads to tumor progression." (PMID 35954489, 2022). "This pathway provides a protective effect to TAMs in the acidic environment and induces CCL8 expression to promote tumor cell migration and metastasis." (PMID 35362482, 2022). "Within the model of HCC, secreted CCL8 acts upon the tumor cells to induce the epithelial-to-mesenchymal transition (EMT), thus potentially facilitating metastasis." (PMID 35362482, 2022). "In TME, TAMs and some tumor-derived vascular growth factors such as VEGF, PDGF, CCL2, and CCL8 promote tumor neovascularization and maintain the tumor growth vascular network." (PMID 35681736, 2022). "A recent study demonstrated a cross talk between tumor cells and tumor-associated macrophages (TAMs) via SIGLEC1, CCL8, and CSF1, suggesting that the gene signature of TAMs correlated with poor clinical outcomes." (PMID 35223504, 2022). "The expression of other M2 marker genes, including Arg‐1, IL‐10, CCL8, Fizz1 and YM‐1, were also upregulated in the tumor from Senp3 cKO mice, as demonstrated by qRT‐PCR analysis." (PMID 33932085, 2022). "In the case of CCL8, the fold-change in expression (tumor-to-adjacent) in N0 vs. N1/2 patients differed significantly by 3.7-fold (0.1 vs. 0.37, p = 0.021)." (PMID 34885960, 2021). "The dynamic role of CCL8 in tumor progression and invasion, by activating NFκB signaling, is widely accepted in different cancer types." (PMID 34959269, 2021). "In TME, TAMs are major sources of CCL8 that support tumor cell survival and increase invasion and stem-like characteristics of GBM cells." (PMID 34692697, 2021). "The conversion of CCL8 into an antagonist by specific proteases in the tumor stroma hampered the therapeutic effect that was envisaged by treatment of tumors with CCL8-expressing oncolytic parvoviruses." (PMID 34503058, 2021). "As for the CCR2 axis, the CCR5 axis is not only related to Treg recruitment, because its ligands (CCL3, CCL4, CCL5 and CCL8) are also involved in tumor progression and metastases." (PMID 33924428, 2021). "CCL8 was an independent prognostic factor for patients with CC, and increased secretion of CCL8 promoted tumor progression." (PMID 34321012, 2021). "Increasingly more findings have demonstrated that the cross-talk of CC chemokines, including CCL8 and CCL21, in BC is significantly associated with carcinogenesis, tumor metastasis and chemoresistance." (PMID 33146700, 2020). "This increase in CCL8/MCP-2 expression in cervical squamous carcinoma cells increases the recruitment of TAM to the hypoxic tumor niche." (PMID 32781743, 2020). "TAM recruitment can also be induced by CCL7 and CCL8, while Treg are recruited into the tumor niche by CCL8 into the tumor niche." (PMID 33182504, 2020). "Gene-gene interactions were detected in the relapse group; CCL5, GZMB, IL2RA, SELE, and CCL8 interacted with CCR5 in both the pCR and relapse groups and were associated with tumour progression, and metastasis." (PMID 33138797, 2020).
tumor (continued). "Analysis of genetic profile demonstrated immune‐related DEGs that closely correlated with tumor microenvironment including immune cell recruitment (CCL8) and trafficking (ICAM‐1)." (PMID 29938166, 2018). "Chemokines such as CCL2, CCL5, CCL7, CCL8, CXCL12 and growth factors, for example, M-CSF, PDGF, and VEGF aggressively recruit blood monocytes at the tumor site, where they distinguish in tumor-associated macrophages." (PMID 29450136, 2017). "The CCL8 expression of dermal fibroblasts was increased by soluble factors, produced by the tumor itself." (PMID 26320180, 2015). "In order to find out which cell types are the potential targets of CCL8, the presence of CCL8 sensitive chemokine receptors was analyzed in the tumorous and several normal constituents of the tumor-host system." (PMID 26320180, 2015). "Despite upregulation of typical M2 markers (arginase I and IL-10), usually associated with tumor progression, SOCS3-deficient macrophages provided tumor protection because of enhanced MCP-2/CCL8 production." (PMID 26579124, 2015). "Increased migration of the examined tumor cell lines was observed when CCL8 was applied as a chemoattractant." (PMID 26320180, 2015). "According to our observations, the migration of tumor cells was inhibited by CCL8 when applied directly and it was increased when added as chemoattractant." (PMID 26320180, 2015). "It is a snapshot of the delicate balance of the stimulating effect of the tumor and the inhibition of CCL8 itself that we see during molecular studies." (PMID 26320180, 2015). "The tumor cells and their interactions can be influenced the expression of CCL8 by dermal fibroblasts, as a significant change in the metastatic microenvironment." (PMID 26320180, 2015). "We found that both stromal and tumor cells expressed CCL8, but the number of positive cells were higher in stroma." (PMID 26320180, 2015). "These included genes known to be expressed by microglia (CCL8, SPP1, IRF7, IL1RAP), macrophages (IL1RN, SPP1, PDPN, IL1RAP, MDK, TFRC, HRH4), and tumor-associated macrophages (IL6, SPP1)." (PMID 22937035, 2012). "An in vivo experiment was performed to validate the function of CCL8 in tumor progression." (PMID 41253786, 2025). "Indeed, the top 30 significantly enriched immune modulators in ME patients included CCL8, a ligand for the tumour infiltrating Treg cells chemokine receptor CCR8, PVR, a ligand for the T cell checkpoint protein TIGIT and ITGA8, which is known to activate TGFb." (PMID 39915477, 2025). "In addition, responsiveness to CCL8 is a feature of the tumor microenvironment, expanding the roster of the pro‐oncogenic targets in tumors." (PMID 40545574, 2025). "Finally, we further clarified the role of mTOR-HIF-1α-CCL8 in pro-tumor effect by TAMs through in vitro and in vivo experiments." (PMID 37884960, 2023). "In addition, lung metastases preferentially comprised neutrophils, potentially related to tumor-derived CCL8." (PMID 37106167, 2023). "Targeting the CCL8/CCR5/mTOR pathway is a promising target for future tumor treatment." (PMID 38136340, 2023). "Moreover, M2 TAMs activated the JAK1/STAT3 pathway and conferred resistance to 5‐FU by increasing the secretion of CCL8 in tumour cells." (PMID 37608500, 2023). "Additionally, [Pyr1] apelin-13 infusion induced CD8+ T-cell infiltration into tumors, resulting in inhibition of tumor growth through C-C Motif Chemokine Ligand 8 expression." (PMID 36776217, 2023). "Therefore, the CAXII/CCL8 axis has been thought to be involved in the progression and metastasis of tumor and a potential therapeutic target." (PMID 37006233, 2023). "Targeting the CCL8/CCR5/mTORC1 pathway is a promising target for future tumor treatment." (PMID 38136340, 2023). "We found that CCL8 accelerated tumor growth and lung metastasis compared to the control group, but this promotion could be blocked by the CCR5 inhibitor, Maraviroc." (PMID 38136340, 2023).
tumor (continued). "In CRC clinical samples, CCL8+ macrophages were enriched evidently in tumor regions." (PMID 38136340, 2023). "CCL8, another cytokine produced by TAMs, has been shown to promote tumor invasion and stemness." (PMID 37884960, 2023). "It should be noted that Ccl7 or Ccl8/12 are depleted in the TME but are retained in tumor cells." (PMID 37012245, 2023). "In addition, CCL8 was involved in the migration, invasion, and stemness of cancer cells in the tumor microenvironment." (PMID 35281057, 2022). "The chemokines CCL2, CCL7, and CCL8 are expressed in many cancer types as well as cancer-associated fibroblasts (CAFs), tumor-associated macrophages (TAMs), MDSCs, and mesenchymal stem cells found in the TME, which support the tumor growth and metastasis." (PMID 35432319, 2022). "In the present study, we demonstrated that high expression levels of CCL8 mRNA in tumor tissues were associated with poor prognosis of patients with stage I–III CRC, implying that CCL8 may be a useful prognostic biomarker for patients with CRC." (PMID 36136589, 2022). "To explore whether CA12 facilitates tumor metastasis by regulating the production of CCL8 in monocytes, we treated CD14+ cells from healthy donors with HepG2 TSN in the presence or absence of the glycolysis inhibitor 2DG, CA12 inhibitor, or siCA12." (PMID 35362480, 2022). "Also, reduced CD44 and CD31 expressions were observed in CCL8 antibody-treated tumors, suggesting that the blocking of CCL8 reduced the THP-1-derived M2-like macrophages-induced increase of tumor onset and angiogenesis." (PMID 35680853, 2022). "Moreover, similarly to the CA12 inhibitor and siCA12, the p38 inhibitor SB202190 markedly abrogated the increase in CCL8 production in tumor-exposed monocytes." (PMID 35362480, 2022). "NEFM transcriptional expression was negatively associated with CCL7, CCL8 and CCL18, which would recruit monocytes to differentiate into tumor-associated macrophages (TAMs) at the tumor site, indicating that NEFM may cause decreased M2 macrophage infiltration." (PMID 34001208, 2021). "Furthermore, modification of CCL8 activity influences tumor histopathology and promotes intravasation, extravasation and metastatic processes." (PMID 34160019, 2021). "Moreover, the expression of all of the MCPs increased along with the advancing T stage and a fold-change in CCL8 expression (tumor-to-adjacent) was higher by 3.7-fold in patients with lymph node involvement." (PMID 34885960, 2021). "We found that CCL8 was more highly expressed in tumor ECs from WT than Apelin-KO mice." (PMID 34234274, 2021). "Our study found a positive correlation between CCL8 expression and levels of M1 macrophages, suggesting that CCL8 may help drive the anti-tumor efficacy of M1 macrophages in the TME." (PMID 34844613, 2021). "To determine if tumor CD200 interacts with CD200R on macrophages to regulate CCL8 production, we generated bone marrow derived macrophages (BMDM) from CD200R–/– and WT mice, co-cultured them with Yumm1.7 tumor cells and measured CCL8 gene expression and protein secretion." (PMID 34692697, 2021). "Cancer cell vaccination studies in animals with CCL8 deficiency have reported that CCL8 accelerates tumor initiation during involution, but no tumor-promoting effect was detected in nulliparous animals." (PMID 34160019, 2021). "The local CCL8-rich environment could promote the selection of tumor cells with metastatic capacity, and the high CCL8 concentration inhibited the migration of tumor cells." (PMID 33688507, 2021). "Our result indicated that increased CCL8 expression might induce CD8 + T cells infiltration into tumor and tumor inhibition." (PMID 34234274, 2021). "Therefore, we analysed CCL8 receptor expression in the tumor microenvironment and consider how the Apelin/CCL8 axis is involved in tumor immunity." (PMID 34234274, 2021).
tumor (continued). "Moreover, CCL8 not only facilitates tumor invasion to adjacent stroma in BC but also intravasation and extravasation, leading to the establishment of secondary growth." (PMID 33146700, 2020). "The expression of CCL8 was significantly correlated with the infiltration levels of macrophages M0, macrophages M1, macrophages M2, neutrophils, CD8+ T cells, and Tregs (which illustrates the relationships between the expression of CCL8 and tumor-infiltrating immune cells)." (PMID 33181717, 2020). "Thus, by establishing a CCL8-gradient, CAFs attract cancer cells towards the tumor margins, precisely where the highest amounts of CCL8 are detected." (PMID 32604738, 2020). "However, chemokines CCL2 and CCL8 can further promote tumor growth and angiogenesis by recruiting and activating tumor‐related macrophages." (PMID 32253815, 2020). "CCL8 is expressed by dermal fibroblasts to modulate tumor‐stroma and tumor‐tumor cross‐talk in the initiation of metastasis, while ICAM is mainly produced and modulated by immune cells or in response to immune cell signal which are absent in monolayer monoculture." (PMID 31192543, 2019). "In univariate analysis high expression of SIGLEC1/CCL8 was significantly associated with shorter DSS, along with Her2 status (HR = 2.1, p = 2.3 ×1010), grade (HR = 1.8, p = 1.9 × 10−9) and tumor size (HR = 1.8, p = 0.002)." (PMID 30930117, 2019). "As a known potent macrophage attractor, CCL8 is abnormally increased in various types of tumours and functionally contributes to tumour metastasis; it has also been determined to be an effective marker to predict the prognosis of tumour patients." (PMID 31263103, 2019). "In order to decide which cell types could be the source of CCL8 production (stromal cells or tumor cells), immunohistochemistry was performed on clinical samples." (PMID 26320180, 2015). "As a consequence of the tumor-host interaction, some of the tumor cells might be able to express CCL8." (PMID 26320180, 2015). "The high CCL8 concentration inhibits the migration of tumor cells." (PMID 26320180, 2015). "CCL8 in return enhances the migration activity of tumor cells as chemoattractant." (PMID 26320180, 2015). "Tumor-associated macrophages (TAMs) are derived mostly from circulating monocytes which are attracted into tumor sites by locally produced chemotactic factors, such as CCL2, CCL5, CCL7, CCL8, and CXCL12, and macrophage colony stimulating factor (M-CSF)." (PMID 24966464, 2014). "We next validated whether CCL8 mediated the pro-tumor effect of TREM2+ TAMs." (PMID 41253786, 2025). "On the other hand, Jun can stimulate apoptosis in a range of cancer cell types and play a tumour-suppressing role, for example, in a manner inversely related to JunD or by transcriptional regulation of senescence- and inflammation-associated genes including IL-1β, TNFα, CCL3 and CCL8." (PMID 39859271, 2025). "CCL8 may also involve neoplasia and inflammatory host responses." (PMID 38960408, 2024). "Gene expression analysis showed that chemokines such as Ccl2 and Ccl8 and cell proliferation markers such as Mki67 and Birc5 were highly expressed in cluster 3, indicating that 8 mg/kg of smTRAIL may induce tumor cell “activation” and secretion of chemokines to recruit immune cells." (PMID 37605148, 2023). "Cxcl2, Ccl2, Ccl3, and Ccl8 can act as chemoattractants for myeloid cell recruitment in tumors, while Csf1, Csf2, and Csf3 are central to controlling the recruitment, proliferation, and differentiation of immunosuppressive myeloid cells, including macrophages and neutrophils in the tumor." (PMID 37138326, 2023). "While CCL8 has been previously found to be produced by stromal fibroblasts stimulated with inflammatory cytokines, the present study showed that, in human HCC, CCL8 was mainly derived from tumor-infiltrating monocytes and macrophages and could be regulated by CA12 expression by these cells." (PMID 35362480, 2022).